RN7SL819P (RNA, 7SL, cytoplasmic 819, pseudogene)
Gene: Miscellaneous RNA gene on chromosome 17 (44,718,861 to 44,719,130, reverse strand). Ensembl gene ENSG00000264251.
Homologues: Orthologues: chimpanzee Metazoa_SRP (97% identical). Paralogues in human: RN7SL811P (84% identical), RN7SL784P (83% identical), RN7SL474P (83% identical), RN7SL774P (83% identical), RN7SL96P (82% identical), Metazoa_SRP (82% identical), RN7SL154P (82% identical), RN7SL488P (82% identical), Metazoa_SRP (81% identical), RN7SL163P (81% identical), RN7SL622P (81% identical), RN7SL835P (81% identical), and 709 more.